ERBB4 (erb-b2 receptor tyrosine kinase 4)
Diseases named in the same sentence as ERBB4 in open-access papers (continued):
Sharing a sentence is not in itself a finding about the gene and the disease.
infection (11 papers, 2015 to 2024). The state of being infected such as from the introduction of a foreign agent such as serum, vaccine, antigenic substance or organism. "Our study also demonstrates the ability of NRG-1/ErbB4 signaling to rescue infection-induced neuropathology in the form of GLT-1 loss via exogenous NRG-1 treatment during Toxoplasma infection, a neuroprotective mechanism that has not been reported previously." (PMID 39095837, 2024). "As previously seen, a percentage of CBNeuts also expressed the main NRG-1 receptor ErbB4 (20–60%), and the kinetics revealed a striking high percentage of neutrophils expressing ErbB4 at 2wpi that significantly dropped as infection progressed." (PMID 39095837, 2024). "Incorporation of the EGF-like domain from neuregulin 1 alpha (NRG1α) in the fiber of adenovirus capsid allowed preferential infection in cells lines expressing ErbB4." (PMID 37819378, 2023). "As such, ErbB4 signaling can limit the accumulation of immune cells at sites of infection in the gut." (PMID 33826403, 2021). "The results showed that Nup98, Nrg1, and erbB4 were upregulated during the acute phase of infection (7 dpi) and decreased at the chronic phase of infection (40 dpi) even though the extent of decrease for Nup98 expression was small." (PMID 31396490, 2019). "Immunofluorescence (IFC) results confirmed the findings of Western blot analysis whereby total ErbB4 protein remained unchanged 12 days after infection." (PMID 29636063, 2018). "Expression of NRG-1 by CBNeuts reveals a distinct brain-specific phenotypic and transcriptomic profile of these cells which also display functional heterogeneity based on age and integrin expression, and NRG-1/ErbB4 signaling play a role in limiting infection-induced neuropathology." (PMID 39095837, 2024). "In order to favour infection of these cells, we considered ErbB4 as a surface target." (PMID 37819378, 2023). "Moreover, we found that cleavage of NUP98 leads to the downregulation of cardioprotective genes Nrg1 and erbB4 in later phase of infection." (PMID 31396490, 2019). "Although addition of the EGF-like domain from NRG1α favoured infection of cells expressing high levels of ErbB4, this was not sufficient to obtain specific infection of primary GABAergic neurons in cell culture or in vivo." (PMID 37819378, 2023). "However, ERBB4, the receptor of NRG1, had a slight decrease at early time-point of infection and decreased dramatically at 7 hpi." (PMID 31396490, 2019). "Real-time quantitative PCR results showed that PbA infection did not change ErbB4 expression in the cortex." (PMID 29636063, 2018). "By using genotype 1b replicon cells as well as an infection-based system we found that while transcript and protein levels of EGFR and ErbB2 were up-regulated or unaffected, respectively, HCV induced a substantial reduction of ErbB3 and ErbB4 expression." (PMID 26886748, 2016). "Flow cytometry results show that siRNA silencing the expression of SGK3, ULK3, ERBB4, STK17B can reduce the infection efficiency of ORFV-GFP virus, while siRNA silencing the expression of MST1R, PAK4, ERBB3 can increase the infection of ORFV-GFP virus efficient." (PMID 35401439, 2022). "Additionally, Nup98, Nrg1, and erbB4 were all upregulated in the murine myocardium during acute/early phase of CVB3 infection, and Nrg-1 and erbB4 were downregulated at a later phase of infection, suggesting a cardioprotective role of this signal cascade in cellular response to infection." (PMID 31396490, 2019). "Innate macrophages and CNS-resident microglia also expressed these molecules while adaptive T cells did not express ErbB4 at any time point; however, a subpopulation of T cells (10–20%) did express NRG-1 which increased over the course of infection." (PMID 39095837, 2024).
infection (continued). "We first checked the transcription of these ErbB members by real-time PCR and found that the transcription levels of EGFR, ErbB2, and ErbB4 did not significantly change in response to SC19 infection, while ErbB3 showed a significant decrease since 2 h post infection." (PMID 27756321, 2016).
neurodevelopmental disorder (9 papers, 2010 to 2025). A behavioral and cognitive disorder with onset during the developmental period that involves impaired or aberrant development of intellectual, motor, or social functions. "In theory, therefore, these findings would seem to suggest that NRG1 and ErbB4 could be promising targets for gene therapy of neurodevelopmental disorders such as Sz." (PMID 32546684, 2020). "Further research is warranted to elucidate the precise mechanisms involved and explore potential therapies targeting the NRG1/ErbB4 pathway, which could mitigate the adverse effects of prenatal morphine exposure and lead to novel therapeutic strategies for neurodevelopmental disorders." (PMID 39109071, 2024).
neurodegenerative disease (7 papers, 2016 to 2025). A disorder of the central nervous system characterized by gradual and progressive loss of neural tissue and neurologic function. "Moreover, we found pathways that mediate fear conditioning and behavior signaling by ERBB2 (p = 0.00000711) and ERBB4 (p = 0.0000106), also involved in the development of neurodegenerative diseases." (PMID 33469418, 2020). "Our finding that 71.4% of people with respiratory onset ALS have insertion in the ERBB4 gene is an important clue to disease mechanism and factors that determine which group of motor neurons are most vulnerable at disease onset, a key issue in neurodegenerative disease research." (PMID 35091648, 2022). "As far as we know, the mRNA levels of NRG1 and ErbB4 have not been investigated during CCH, but similar changes have been reported in other animal models of neurodegenerative diseases." (PMID 29875654, 2018).
metabolic disorders (5 papers, 2017 to 2025). "The ERBB4 gene has been found to be a promising diagnostic and therapeutic target for metabolic disorders." (PMID 40677584, 2025). "The expression pattern at rs11031005 (FSHβ locus) in fat predicted a relationship to endocrine function and the pattern for rs2178575 (ERBB4 locus) in skin predicted a relationship to metabolic disease." (PMID 28068351, 2017). "Notably, ERBB4, with significant MR estimates and cis colocalization for BMI (IVW: − 0.26, 95% CI: − 0.378 to − 0.138), has previously been linked to metabolic disorders and obesity." (PMID 40032831, 2025).
brain disorder (4 papers, 2015 to 2019). A disease affecting the brain or part of the brain. "Thus, the S100A4-induced ErbB4 modulation may potentially play a role in many brain disorders, holding promise for future therapeutic applications." (PMID 30083275, 2018).
heart disease (3 papers, 2015 to 2023). "Thus it is likely that ErbB2/ErbB4 pathway is chronically activated in these conditions and its blockage by trastuzumab treatment may empathize trastuzumab-related cardiotoxicity in elder patients with undiagnosed heart diseases." (PMID 26836985, 2016).
renal disease (3 papers, 2022 to 2025). "While these studies support the importance of ERBB4 in renal diseases in mice, limited human results are available to support these findings." (PMID 38768139, 2024).
neurologic diseases (2 papers, 2024). "In summary, disruption of the NRG1/ERBB4 (ALS19) axis offers therapeutic possibilities for both cancer and neurologic diseases such as ALS." (PMID 38369520, 2024).
genetic diseases (1 paper, 2010). "Future studies are required to determine the contribution of ErbB4 exon 3 skipping to human neurodevelopment and genetic diseases, but our findings suggest that ErbB4 del. transcripts exist as attractive potential modulators of ErbB4 signaling." (PMID 20886074, 2010).
ERBB4 also shares sentences with these, for which no sentence is quoted: hepatocellular carcinoma (6 papers); astrocytoma (3); lymphoma (3); meningioma (3); multiple sclerosis (3); anaplastic thyroid cancer (2); Angelman syndrome (2); Fibroadenoma (2); granulosa cell tumor (2); Hepatic steatosis (2); Hyperglycemia (2); Insulin resistance (2); leukemia (2); malignant peripheral nerve sheath tumor (2); multiple myeloma (2); papillary carcinoma (2); phyllodes tumor (2); polycystic ovarian syndrome (2); small cell lung carcinoma (2); acute myeloid leukemia (1); allergic reactions (1); anaplastic carcinomas (1); aortic stenosis (1); aortic valve stenosis (1); Atrophy (1); autoimmune disease (1); Autoimmunity (1); B-cell lymphomas (1); Bacterial Infection (1); Behavioral variant frontotemporal dementia (1).
A further 73 diseases each share a sentence with ERBB4 in 1 paper.